STAT3 (signal transducer and activator of transcription 3)
Diseases named in the same sentence as STAT3 in open-access papers (continued):
Sharing a sentence is not in itself a finding about the gene and the disease.
tumor (continued). "Signal transducer and activator of transcription 3 (STAT3) is a key player in the mechanism of tumor-induced immune deregulation characterized by the paucity of immunological danger signals essential for immune activation and escaping of cancer cells from natural immune surveillance." (PMID 28659794, 2017). "The correlation between STAT3 PTMs and tumor grades would be an additional biomarker for the exactly evaluation of the PCa stages and the optimal treatment options: Watchful Waiting for the indolent tumor, prostatectomy or hormone therapy for the aggressive ones." (PMID 28489571, 2017). "Our results imply that niclosamide-mediated inhibition of STAT3 may contribute to the overall efficacy of niclosamide as a tumor suppressor to repress U-87 MG cell proliferation and promote cell death." (PMID 28877265, 2017). "Furthermore, western blot analyses of the whole tumor lysates revealed a marked inhibition of p-Stat3 by nifuroxazide treatment." (PMID 28055016, 2017). "A novel tumor suppressive role for Stat3 in Kras-driven lung AC was recently identified." (PMID 28574510, 2017). "Moreover, we investigated the correlation between SHP2 and JAK2/STAT3 signaling in vitro and in tumor tissues from patients with CRC." (PMID 29242509, 2017). "For example, Wang and collaborators reported that CD133+ ovarian CSCs have the IL-23/IL-23 receptor axis activated, and the activation of this pathway promotes self-renewal and formation of ovarian CSCs by activation of the signaling pathways STAT3 and NFκB, thus contributing to tumor progression." (PMID 28819364, 2017). "However, the concentrations of LY5 necessary to observe an anti-tumor effect in vivo were discordant with the concentrations of LY5 necessary for inhibition of STAT3 phosphorylation." (PMID 28750090, 2017). "After FICTION with FVIII and Stat3 dual immunofluorescence reaction, and FISH with the Stat3 gene (red) and chromosome 9q34.11 (green) probes, tumor vessels showed a merge fluorescent colocalization signal in some vascular tracts, while in other tracts the signals were separate." (PMID 28415725, 2017). "We tested the hypothesis that inhibitors of STAT3 activation, such as CuB, could overcome this drug resistance and enhance the cytotoxic effects of chemotherapeutic drugs in cytokine-dependent MM tumor cells." (PMID 27418139, 2017). "VEGF, which is among the target of STAT3, also contributes to tumor angiogenesis." (PMID 28445952, 2017). "In solid tumors, tumor cells produce transcription factors like NF-κB, signal transducer and activator of transcription 3 (STAT3), and hypoxia-inducible factor 1α (HIF-1α), all of which have a profound effect on the recruitment, differentiation, and maturation of infiltrating leukocytes." (PMID 28471401, 2017). "STAT3 subtype specific gene signatures could serve as potential biomarkers for determining the specific subtype of TNBC tumor and appropriate choice of STAT3 inhibition and chemotherapy for personalized treatment." (PMID 28030809, 2017). "STAT3, a cytoplasmatic latent transcription factor, is a hub protein for several oncogenic signalling pathways and up-regulates the expression of numerous genes involved in tumor cell proliferation, angiogenesis, metastasis and cell survival." (PMID 28489571, 2017). "In addition, lncRNA-ATB promotes organ colonization of disseminated tumor cells by binding to interleukin-11 mRNA and triggering the STAT3 signaling pathway." (PMID 29108251, 2017). "Though inactive, cytoplasmic Stat3 might be tumor suppressive, the contribution of activated nuclear Stat3 needs to be further evaluated." (PMID 28574510, 2017). "The activation of STAT3 in malignant tumour cells may be one of the important molecular markers for tumour progression." (PMID 29127353, 2017).
tumor (continued). "To determine whether SLE affects STAT3 activation, we examined the expression of phosphorylated STAT3 in tumor tissues by immunoblotting." (PMID 28596565, 2017). "However, the expression of STAT3 and pSTAT3 proteins remained low until the gastric mucosa reached the tumor stage." (PMID 28061480, 2017). "STAT3 engages hypoxia-responsive gene transcription in tumor cells." (PMID 28978186, 2017). "However, other studies suggest that STAT3 signalling in immune cells is also important for the initiation of inflammatory responses, which are essential to initiate and educate anti-tumour T-cell responses." (PMID 28276425, 2017). "Aberrant G6PD could stimulate cell proliferation and tumor growth by activating the G6PD-ROS-p-STAT3-CyclinD1 signaling pathway." (PMID 29312589, 2017). "Activation of both Stat1 and Stat3 signalling pathways in tumour cells by mMDSCs may account for the induction of EMT/CSC phenotype as assessed by strong upregulation of EMT-related genes such as Vimentin, CK14 and Twist." (PMID 28382931, 2017). "Interestingly, the expression levels of GPRC5A and p-STAT3 were inversely correlated, even in different area from the same tumor tissue." (PMID 28270740, 2017). "Transcription factor Stat3 has been involved in the tumor cell growth and progression." (PMID 28360411, 2017). "We have identified an unexpected role of Stat3 in the regulation of centrosome clustering, and this role of Stat3 may be critical in identifying tumours that are sensitive to Stat3 inhibitors." (PMID 28474672, 2017). "Therefore, in our study, the p-STAT3 expression was considered for subsequent biological behavior, such as tumor cell proliferation." (PMID 29100435, 2017). "In addition, the number of CD3+CD4+CD25+Tregs in PBMCs from the tumor-bearing BALB/c mice immunized with STAT3-blocked HCC vaccine decreased." (PMID 29115974, 2017). "Indeed, STAT3 depletion in DCs improves cancer immunotherapy, by enhancing their ability to induce tumor antigen-specific T cells and promoting their resistance to cancer cell-derived inhibitory factors." (PMID 28435516, 2017). "From these findings we speculated that inactivation of JAK2/STAT3 or Src/STAT3 signaling pathway may be critical for SFN-induced anti-tumor effects in GBM cells." (PMID 28054986, 2017). "It has been previously reported that VP exhibited in vivo selectivity for killing tumor cells in part by impairing the global clearance of high-molecular weight oligomerzed proteins, particularly p62 (a sequestrome involved in autophagy) and Stat3." (PMID 28404908, 2017). "The actions of MyD88 in regulating the expression of these factors is likely to involve both direct and indirect mechanisms, mainly coordinating the interplay between NF-κB, HIF1α, and STAT3 transcription factors, which are well known for its roles in tumor development and inflammation." (PMID 28662055, 2017). "In addition, PHS-based inhibition of EMT was attributable to the downregulation of the EGFR/JAK1/STAT3 signaling axis, as validated by immunoprecipitation assays and breast tumorigenesis mice models." (PMID 29100426, 2017). "In addition to gametogenesis, PIWIL2 can promote tumorigenesis through upregulating several signal transduction pathways and inhibiting apoptotic death of tumor cells via activation of Stat3/Bcl-XL pathway." (PMID 28545024, 2017). "Compared with the tumors from the control group, tumor tissues with miR-218 overexpression showed lower levels of phosphorylated STAT3 and Ki67, suggesting that overexpressing miR-218 inhibited the STAT3 signaling and reduced tumor growth in vivo." (PMID 28830450, 2017). "STAT3 inhibition was facilitated by twice-weekly intra-tumour injections of the siRNA." (PMID 28423603, 2017). "In addition to direct activation of STAT3, other mechanisms promoting tumor angiogenesis are facilitated by STAT3." (PMID 28978186, 2017).
tumor (continued). "Tumor cells are able to induce a suppressive phenotype by STAT3-signaling which leads to secretion of IL-6 and may suppress the activity of several cell types relevant to antigen presentation and cytotoxic T-cell responses." (PMID 28402937, 2017). "In HPV-driven carcinogenesis, IL-6-induced JAK/STAT3- and C/EBPβ-driven stromal inflammation may play a key role in promoting tumor progression." (PMID 28895886, 2017). "We measured tumor phospho-Tyr705-STAT3 to determine whether the decrease in IL-6 levels resulted in the suppression of STAT3 activation." (PMID 28416734, 2017). "In tumor, STAT3 could contribute to cancer development and progression, inhibit apoptosis of tumors, and help tumor escape immune system by suppressing the immune response." (PMID 28630636, 2017). "In addition, the STAT3 signalling pathway regulates tumour invasion and metastasis by regulating MMP2 expression." (PMID 28423603, 2017). "Several studies have indicated constitutively activated STAT3 in human tumor samples." (PMID 29207645, 2017). "In order to confirm whether anti-tumor effect of fluspirilene is due to only STAT3 inhibition, Alamar blue proliferation assay was performed using fluspirilene, STAT3 siRNA, and their combination." (PMID 29340087, 2017). "Considering that IL-10 could enhance proliferation of MM cells, and reduce Adriamycin-induced cell death, we hypothesized that CuB-mediated inhibition of the STAT3 pathway might synergistically enhance the anti-tumor activity of Adriamycin." (PMID 27418139, 2017). "In MM tumor cells resistant to bortezomib, no such mutations were found, rather a constitutive activation of the STAT3 signaling pathway and in turn, the upregulation of the β5 subunit." (PMID 28797244, 2017). "STAT3 plays a critical role in tumor development, angiogenesis, and metastasis." (PMID 28445971, 2017). "In addition, blockade of STAT3 activity leads to the inhibition of tumor growth and tumor-initiating potential in CRC." (PMID 28209178, 2017). "Activated STAT3 in turn promotes tumor growth through STAT3-responsive genes." (PMID 28747781, 2017). "Finally, we showed that DHA targeted STAT3 signaling by strongly inhibiting STAT3 phosphorylation in tumor cells as well as in PBMCs and DCs." (PMID 28435516, 2017). "Moreover, our data in this study further confirmed that the enhanced STAT3 activation is crucial for tumor-promoting function of neutrophils." (PMID 28432279, 2017). "Our data suggest that FRK could promote the inhibition of cell growth and migration by suppressing the activation of various signaling pathways, and more significantly the STAT3 signaling pathway and the tumor suppressor role of FRK could be tissue dependent." (PMID 29348886, 2017). "The inflammatory milieu of the tumor microenvironment affects different intracellular master regulators of TAMs such as Signal Transducer and Activator of Transcription factors (STAT3 and STAT6 for M2, STAT1 for M1 polarization), the nuclear factor-κB (NF-κB), RORC1, and HIF-1." (PMID 28197019, 2017). "Further data showed the c-Src/STAT3 signaling pathway may be involved in miR-27b-3p-ROR1-mediated tumor cell proliferation." (PMID 29212222, 2017). "In our analysis, tumor cell nuclear STAT3 expression directly correlated with an improved disease-free and overall survival in patients treated with cisplatin-based chemoradiotherapy, while there was no such correlation for patients treated with radiotherapy alone." (PMID 28903353, 2017). "Finally, MT/ShcA313F/313F cells represent tumours that were debilitated in tyrosine kinase/ShcA signalling but that hyperactivated compensatory signalling pathways (both STAT3 dependent and independent) to re-acquire immune suppression." (PMID 28276425, 2017). "Furthermore, Chop deficiency promotes the anti-tumor activity of tumor-infiltrating myeloid-derived suppressor cells (MDSC) by decreasing IL-6 and phospho-STAT3, delaying tumor progression." (PMID 28860159, 2017).
tumor (continued). "In addition, other studies have also shown that it inhibits tumor cell growth and distant metastasis, but promotes tumor cell apoptosis by inhibiting STAT3 phosphorylation, the transcription and replication of DNA mediated by p-STAT3." (PMID 28797050, 2017). "STAT3 function has increasingly become focus of anti‐tumour research." (PMID 27624867, 2017). "STAT3 inhibition attenuated tumour growth and metastasis and prolonged the survival of these mice." (PMID 28423603, 2017). "Administration of IL12 to mice bearing hepatocellular carcinoma cell–based tumors alters the functional phenotype of M2-like TAMs by downregulation of Stat3 and its downstream transcription factor c-myc, thereby reducing the production of tumor-promoting cytokines and inhibiting tumor growth." (PMID 28467800, 2017). "p-STAT3 level was measured from tumour cells after 24 h of irradiation using flowcytometry." (PMID 29070894, 2017). "By virtue of interacting with other transcription factors (e.g., NF-B), STAT3 is known to mediate crosstalk between tumor cells and inflammatory cells within the tumor microenvironment and promote the development and progression of multiple types of human cancers." (PMID 29371911, 2017). "Here, we silenced STAT3 in tumor cells using shRNA constructs." (PMID 29245982, 2017). "Moreover, IL-6 contributes to the malignancy of tumor cells bysustaining the phosphorylation of signal transducer and activator of transcription 3(STAT3)." (PMID 28659496, 2017). "Hyperactivation of downstream signaling pathways such as mitogen activated protein kinases (MAPK), phosphoinositol kinase 3 (PI3K) and signal transducer and activator of transcription 3 (STAT3), promotes tumor cells growth, differentiation, migration, and evasion of apoptosis." (PMID 29137309, 2017). "In contrast to Stattic, metformin's action on tumor cells is not limited to STAT3 inhibition." (PMID 28030813, 2017). "Finally, treatment of athymic nude mice bearing SCC xenografts with KIR-ESS peptide concomitantly reduced tumor growth and activated STAT3 levels." (PMID 28445952, 2017). "Interestingly, NK cell-mediated anti-tumor effects were induced by inoculation with STAT3-blocked HCC cells in mice, indicating that blocking STAT3 would augment the immunogenicity of HCC cells, in addition to reversing HCC-mediated immune suppression." (PMID 29115974, 2017). "The ablation of STAT3 expression through the use of conditional knockout mice or selective STAT3 inhibitor significantly reduced the expansion of MDSCs and increased T cell responses in tumor-bearing mice." (PMID 28928739, 2017). "So whether a patient's tumor is driven by STAT3, MYC, Notch or a combination, they could still be treated with a CCT inhibitor since the chaperonin is essential for these proteins to reach functional status." (PMID 29299146, 2017). "Bazedoxifene was found to disrupt IL-6 and GP130 interaction and STAT3 activation, therefore, we investigated whether Bazedoxifene blocks tumor invasion and angiogenesis." (PMID 28672024, 2017). "Genetic deletion of Stat3 and Stat6 impaired tumour development and invasion in vivo." (PMID 29065107, 2017). "Moreover, NF-κB and STAT3 are crucial for controlling the abilities to resist apoptosis-based tumor surveillance as well as regulating angiogenesis and invasiveness in preneoplastic and malignant cells." (PMID 28594363, 2017). "In conclusion, PRSS8 acts as a tumor suppressor by inhibiting Sphk1/S1P/Stat3/Akt signaling pathway, and could be used as a biomarker to monitor colorectal carcinogenesis and predict outcomes." (PMID 27050145, 2016). "Studies have found that STAT3 gene has low expression in majority of tumour cells, suggesting that reduced STAT3 gene expression may be involved in tumorigenesis." (PMID 27129294, 2016).
tumor (continued). "Treatment of tumor cell lines with a platinum-containing STAT3 inhibitor (CPA-7) or expression of dominant-negative STAT3 (STAT3β) splice variant resulted in increased secretion of chemoattractants, such as RANTES, IFN-γ-inducible protein (IP-10), MCP-1, MIP-2, and T cell activation (TCA)-3." (PMID 27148255, 2016). "In vitro and in vivo functional assays performed with HCC cell lines demonstrated that autocrine expression of hGH or hPRL in HCC cells increased STAT3 activation, oncogenicity and tumor growth while functional antagonism with hGH-G120R significantly reduced these parameters." (PMID 27102295, 2016). "In univariate analysis, high ph-STAT3 but not ph-STAT1 tumour cell expression was significantly associated with improved CSS." (PMID 27769057, 2016). "However, we demonstrate that expression is highly compartmentalized to distinct subpopulations of cells, and that Stat3 retains a suppressive effect on mCLCA5 expression in 4T1 tumour cells." (PMID 27711075, 2016). "In other words, STAT3 activation in tumor cells mediates the effect of macrophages on tumor cells." (PMID 27793010, 2016). "We also evaluated whether the clinical outcome of patients with solid tumors differed between STAT3 phosphorylation state and between different tumor types." (PMID 26959884, 2016). "Since STAT3 regulates the expression of various tumor growth related oncogenic genes and plays a key role in cell proliferation, we investigated whether RY10-4 can regulate constitutive STAT3 activation in HepG2 cells." (PMID 26974964, 2016). "Inhibition of the JAK2/STAT3 pathway in PTEN-deficient prostate tumors led to senescence-associated cytokine network reprogrammed, and improved the efficacy of docetaxel-induced senescence by triggering a strong anti-tumor immune response." (PMID 26919108, 2016). "IL-6 and the activated JAK/STAT3 pathway may serve as efficient targets for blocking or suppressing tumour self-seeding." (PMID 26623559, 2016). "Interestingly, suppression of IL-6 or OSM induced STAT3 signaling in GBM following conventional therapy suppressed tumor growth and stemness-related factors, respectively." (PMID 26742077, 2016). "In head and neck tumor cells, STAT-3 is overexpressed in comparison to others tumor cells." (PMID 27834913, 2016). "Compared with the blank control group, the tumour volumes were significantly decreased in STAT3 group [624.21±54.21 compared with 1421.57±241.06 mm3], CDDP group [603.72±82.41 compared with 1421.57±241.06 mm3] and combination group [376.18±68.91 compared with 1421.57±241.06 mm3] respectively." (PMID 27129294, 2016). "Consequently, several research teams have evaluated STAT3 targeting drugs as a means to interfere with these processes and as such put a brake on tumor progression." (PMID 27029037, 2016). "Importantly, suppression of SNHG5 expression not only exerts a strong anti-proliferative effect and induces apoptosis, impacting key survival pathways such as the STAT3 pathway in vitro, but also reduces tumour progression in vivo." (PMID 28004750, 2016). "Although there is evidence that STAT3 is activated in GAMs and may be responsible for the M2 phenotype, our data demonstrate that STAT3 also influences an M1 anti-tumor response." (PMID 26967393, 2016). "Combination of STAT3 inhibitor together with low dose epigenetic modifiers such as 5aza, might result in a more specific reversal of the epigenome and derepression of tumor suppressors, thus deserves further clinical trial in GC." (PMID 27528092, 2016). "STAT3 is known to limit all aspects of the NK response, but in this review, we focus on the effects of STAT3 in the context of immune surveillance of cancer and modulation of NK activity in the tumor microenvironment." (PMID 27148255, 2016). "STAT3 targeting in tumors may therefore also have unanticipated, deleterious effects on tumor immunity." (PMID 27148255, 2016).